FBXO9 (F-box protein 9)
Description:
Substrate recognition component of a SCF (SKP1-CUL1-F-box protein) E3 ubiquitin-protein ligase complex which mediates the ubiquitination and subsequent proteasomal degradation of target proteins and plays a role in several biological processes such as cell cycle, cell proliferation, or maintenance of chromosome stability. Ubiquitinates mTORC1-bound TTI1 and TELO2 when they are phosphorylated by CK2 following growth factor deprivation, leading to their degradation. In contrast, does not mediate ubiquitination of TTI1 and TELO2 when they are part of the mTORC2 complex. As a consequence, mTORC1 is inactivated to restrain cell growth and protein translation, while mTORC2 is the activated due to the relief of feedback inhibition by mTORC1. Plays a role in maintaining epithelial cell survival by regulating the turn-over of chromatin modulator PRMT4 through ubiquitination and degradation by the proteasomal pathway. Regulates also PPARgamma stability by facilitating PPARgamma/PPARG ubiquitination and thereby plays a role in adipocyte differentiation (By similarity).
Synonyms: FBX9; VCIA1; NY-REN-57; dJ341E18.2
Tractability: PROTAC: ubiquitination databases record sites on it.
Gene: Protein-coding gene on chromosome 6 (53,051,991 to 53,100,873, forward strand). Ensembl gene ENSG00000112146.
Subcellular location: Cytoplasm
Subcellular location (Human Protein Atlas): Centrosome
Pathways (Reactome):
Immune System: Antigen processing: Ubiquitination & Proteasome degradation
Metabolism of proteins: Neddylation
Gene Ontology:
Molecular function: protein binding; ubiquitin-like ligase-substrate adaptor activity; ubiquitin-protein transferase activity
Biological process: proteasome-mediated ubiquitin-dependent protein catabolic process; protein K48-linked ubiquitination; protein ubiquitination; regulation of TOR signaling; SCF-dependent proteasomal ubiquitin-dependent protein catabolic process
Cellular component: cytoplasm; SCF ubiquitin ligase complex; cytosol; ubiquitin ligase complex
Genetic constraint (gnomAD): Loss-of-function variants: 14 observed, 33.65 expected, observed/expected ratio (o/e) 0.42, 90% interval 0.27 to 0.65. The upper end of that interval is the gene's LOEUF score, 0.65, which puts it in group 2 of 6, group 1 being the genes least tolerant of losing a copy. Missense variants: 316 observed, 364.38 expected, observed/expected ratio (o/e) 0.87, 90% interval 0.79 to 0.95. Synonymous variants: 104 observed, 118.73 expected, observed/expected ratio (o/e) 0.88, 90% interval 0.75 to 1.03.
Homologues: Orthologues: chimpanzee FBXO9 (99% identical), macaque FBXO9 (99% identical), dog FBXO9 (95% identical), pig FBXO9 (93% identical), rabbit FBXO9 (92% identical), guinea pig FBXO9 (92% identical), rat Fbxo9 (92% identical), mouse Fbxo9 (91% identical), tropical clawed frog fbxo9 (79% identical), zebrafish fbxo9 (68% identical), Drosophila melanogaster CG5961 (34% identical).
Diseases named in the same sentence as FBXO9 in open-access papers:
FBXO9 is named in the same sentence as 20 diseases in open-access papers, as found by Europe PMC text mining. Sharing a sentence is not in itself a finding about the gene and the disease. The quoted sentences say what the papers report.
multiple myeloma (5 papers, 2013 to 2024). "The overexpressed FBXO9 caused increased proliferation and survival in multiple myeloma (MM), while loss of FBXO9 promoted AML development." (PMID 36774506, 2023). "FBXO9 may be associated with patient survival in multiple myeloma, is linked to adipocyte development, and targets peroxisome proliferator-activated receptor gamma (PPARγ) for degradation." (PMID 34480022, 2021). "FBXO9 tends to exhibit oncogenic behavior in conditions such as multiple myeloma and hepatic carcinoma, although its role in various diseases (including cancer) is largely overlooked." (PMID 38486234, 2024). "Compared with its role in lung cancer, FBXO9 presents higher expression levels and oncogenic activity in other conditions, such as multiple myeloma and hepatocellular carcinoma." (PMID 38486234, 2024). "Aberrant expression of FBXO9 to regulate mammalian target of rapamycin signaling by targeting Tel2 and Tti1 degradation promotes survival of multiple myeloma cells." (PMID 34480022, 2021). "Surprisingly, TELO2, which encodes Tel2, a well-identified substrate for FBXO9 in multiple myeloma, demonstrated no significance in this analysis." (PMID 38136595, 2023).
hepatocellular carcinoma (3 papers, 2022 to 2024). A malignant tumor that arises from hepatocytes. "On the contrary, FBXO9 has been implicated in driving drug resistance in hepatocellular carcinoma." (PMID 38136595, 2023). "This inconsistency is likely due to different cancer types, as FBXO9 was found to overexpress in hepatocellular carcinoma." (PMID 38136595, 2023). "However, the function and molecular mechanism of FBXO9 in hepatocellular carcinoma (HCC) remain unclear." (PMID 35847937, 2022).
leukemia (3 papers, 2019 to 2022). A malignant (clonal) hematologic disorder, involving hematopoietic stem cells and characterized by the presence of primitive or atypical myeloid or lymphoid cells in the bone marrow and the blood. "FBXO9 not only plays a role in leukemia initiation, but also functions to maintain AML activity and promote disease progression." (PMID 35008940, 2022). "Conditional knockout of FBXO9 in AML mouse model reveals that FBXO9 plays a functional role not only in leukemia initiation, but also in AML maintaining and disease progression." (PMID 32674429, 2020). "Not only did Fbxo9 play a role in leukemia initiation but it also functioned to maintain AML activity and promote disease progression." (PMID 31684170, 2019). "To study the role of Fbxo9 in AML, we developed a conditional knockout (cKO) mouse model and monitored the leukemia response in vivo." (PMID 31684170, 2019). "As AML is the second most common childhood leukemia, we utilized the TARGET pediatric study of 237 pediatric AML patients to analyze FBXO9 expression and again found downregulation of FBXO9 in all AML subtypes, except patients with normal karyotype." (PMID 31684170, 2019).
lung carcinoma (3 papers, 2020 to 2024). "A significant association was observed between decreased FBXO9 expression and adverse survival outcomes in patients with lung cancer (P = 0.004)." (PMID 38486234, 2024). "Our findings highlight the significant role of FBXO9 in the regulation of V-ATPase activity and provide insights into the molecular mechanisms underlying the suppression of lung cancer metastasis." (PMID 38486234, 2024). "In contrast, downregulation of FBXO9 had the opposite effect on the cancer phenotypes, promoting lung cancer metastasis in H1299 cancer cells employing a similar mouse model." (PMID 38486234, 2024). "Overall, our comprehensive analyses of mRNA and protein levels consistently demonstrated that FBXO9 is significantly downregulated in lung cancer." (PMID 38486234, 2024). "This study identified FBXO9 as a crucial regulator that suppresses lung cancer cell migration, tumor sphere growth and restricts metastasis." (PMID 38486234, 2024). "The biological activities of FBXO9 including inhibition of lung cancer cell migration, retardation of tumor sphere growth, and restriction of metastasis, were demonstrated in a preclinical setting." (PMID 38486234, 2024). "Overall, our observations strongly suggested that FBXO9 serves as a suppressor of lung cancer cell migration but had a limited impact on cancer cell survival." (PMID 38486234, 2024). "Dataset analysis confirmed a significant reduction in FBXO9 mRNA expression in lung cancer cases (P = 0.021)." (PMID 38486234, 2024). "The correlation between decreased FBXO9 expression and unfavorable survival outcomes further emphasized the clinical importance of our findings, thus highlighting FBXO9 as a promising prognostic marker and a potential therapeutic target for lung cancer." (PMID 38486234, 2024). "Our investigation aimed to understand the impact of FBXO9 on the Wnt/β-catenin pathway in lung cancer cells." (PMID 38486234, 2024). "It has been found that FBXO9 affects the metastasis of lung cancer cells by participating in the assembly process of the Vacuolar-type H + -ATPase (V-ATPase), thus influencing the prognosis of lung cancer patients." (PMID 38957810, 2024). "This study underscored the crucial role of FBXO9 in controlling V-ATPase assembly and proposed a molecular blueprint to clarify the role of FBXO9 in combating lung cancer cell metastasis." (PMID 38486234, 2024). "We initially reduced FBXO9 expression in A549 lung cancer cells by siRNA transfection to investigate the effect of ATP6V1A ubiquitination on V-ATPase." (PMID 38486234, 2024). "Similar results were obtained when overexpressing full-length FBXO9 and FBXO9-ΔF in A549 and H1299 lung cancer cells." (PMID 38486234, 2024). "We have determined that the reduced expression of FBXO9 in lung cancer cells leads to intracellular acidification, which in turn activates Wnt signaling and EMT." (PMID 38486234, 2024). "FBXO9 plays a crucial role in inhibiting lung cancer cell migration, tumor sphere growth, and metastasis." (PMID 38486234, 2024). "Our study proposes that FBXO9 plays a role in mitigating lung cancer metastasis, which is supported by several important observations." (PMID 38486234, 2024). "Conversely, the depletion of Fbxo9 or FBXO9 using shRNA in 889DTC or H1299 cells significantly increased cancer cell migration but had minimal effects on the survival of lung cancer cells." (PMID 38486234, 2024). "Collectively, our findings provide evidence that FBXO9 functions as an inhibitor and effectively suppresses lung cancer cell migration, tumor sphere growth, and overall metastasis in cell cultures and mouse models." (PMID 38486234, 2024). "Hence, these in vivo results confirm the potential role of FBXO9 as an inhibitory protein against the migration, tumor sphere growth, and metastasis of lung cancer cells by promoting ATP6V1A ubiquitination." (PMID 38486234, 2024).
lung carcinoma (continued). "Finally, we established a correlation between lower FBXO9 levels and poorer survival outcomes in patients with lung cancer." (PMID 38486234, 2024). "This implies that targeting the excessively activated V-ATPase in lung cancer cells, due to reduced FBXO9 expression, could present a potential therapeutic avenue for controlling lung cancer metastasis." (PMID 38486234, 2024). "This study explored the functional role of FBXO9 in lung cancer." (PMID 38486234, 2024). "We hypothesized that a direct blockade of V-ATPase could effectively mitigate lung cancer metastasis after confirming the inhibitory effect of FBXO9 on the Wnt/β-catenin signaling pathway through targeted V-ATPase inhibition." (PMID 38486234, 2024). "This study investigated the tumor-suppressive functions of FBXO9 in lung cancer." (PMID 38486234, 2024). "First, overexpression of FBXO9 in lung cancer cells reduced the migration of these cells in vitro." (PMID 38486234, 2024). "This suggests that FBXO9 could potentially serve as a prognostic biomarker for lung cancer; however, further validation with additional samples is required." (PMID 38486234, 2024). "Therefore, we focused on the suppressive effect of FBXO9 on lung cancer cells via its ubiquitin ligase activity to better understand how FBXO9 controls lung cancer." (PMID 38486234, 2024). "Furthermore, FBXO9 expression was low in lung cancer tissues and inversely correlated with the survival rates of patients with lung cancer." (PMID 38486234, 2024). "Identifying the specific molecular mechanisms and signaling pathways influenced by FBXO9 could lead to the development of targeted therapies to mitigate lung cancer progression and metastasis." (PMID 38486234, 2024). "This suggested that FBXO9 represents a potential prognostic factor for lung cancer." (PMID 38486234, 2024). "Collectively, these findings provide substantial evidence supporting the significant role of FBXO9-mediated ATP6V1A ubiquitination (which hinders V-ATPase assembly) in suppressing Wnt/β-catenin signaling and EMT in lung cancer cells." (PMID 38486234, 2024). "However, the role of FBXO9 in the metastasis of lung cancer remains unclear." (PMID 38486234, 2024). "As previous experiments showed that FBXO9 suppresses V-ATPase through ATP6V1A ubiquitination, we sought to explore the relationship between FBXO9 and V-ATPase in the regulation of Wnt/β-catenin signaling in lung cancer cells." (PMID 38486234, 2024). "In contrast, depletion of FBXO9 reduced ATP6V1A ubiquitination, resulting in increased V-ATPase assembly and vesicular acidification, thus promoting pro-metastatic Wnt signaling and metastasis of lung cancer cells." (PMID 38486234, 2024). "Importantly, the direct inhibition of FBXO9-mediated ATP6V1A ubiquitination by an interaction inhibitory peptide not only prevents cancer cell migration and sphere formation but also hinders the metastasis of lung cancer cells in a mouse model." (PMID 38486234, 2024).
acute leukemia (1 paper, 2024). A clonal (malignant) hematopoietic disorder with an acute onset, affecting the bone marrow and the peripheral blood. "Previous studies have shown that FBXO9 expression is reduced in the bone marrow of patients with acute leukemia." (PMID 38486234, 2024).
Epileptic encephalopathy (1 paper, 2018). A condition in which epileptiform abnormalities are believed to contribute to the progressive disturbance in cerebral function. "The top-ranked probes related to 25 genes including HNRNPL, RASSF5, CD3D and KALRN involved in immune signalling pathways, in addition to TBC1D24, FBXO9 and VIPR2 previously linked to epileptic encephalopathy." (PMID 29484035, 2018).
myelodysplastic syndrome (1 paper, 2019). A clonal hematopoietic disorder characterized by dysplasia and ineffective hematopoiesis in one or more of the hematopoietic cell lines. "Additionally, when compared to healthy bone marrow (HBM), CML, and myelodysplastic syndrome (MDS), FBXO9 showed decreased expression." (PMID 31684170, 2019).
ovarian carcinoma (1 paper, 2023). A malignant neoplasm originating from the surface ovarian epithelium. "Specifically, FBXO9 might be a putative suppressor of ovarian cancer, at least partially via mediating DNA damage repair." (PMID 38136595, 2023).
pancreatic cancer (1 paper, 2026). "Meanwhile, the expression of FBXO9 is decreased in pancreatic cancer tissues in comparison to normal tissues." (PMID 41646985, 2026).
prostate carcinoma (1 paper, 2014). A carcinoma that arises from epithelial cells of the prostate gland. "We then selected six genes (HNRNPH1, DSC2, FBXO9, MANEA, OR51E1, PRR15L) for validation by qRT-PCR that were over-expressed in prostate cancer across all datasets and showed high fold changes in our microarray." (PMID 25003216, 2014).
tumor (8 papers, 2019 to 2026). "One previous study reported loss of heterozygosity (LOH) of the FBXO9 gene in OV, which is associated with advanced tumor type, histological severity, tumor stage progression, and increased tumor metastasis." (PMID 38136595, 2023). "Through interrogation of the proteomic changes occurring in murine AML tumor cells upon loss of Fbxo9, we identified various proteasome components and proteasome-related proteins that were upregulated." (PMID 31684170, 2019). "Furthermore, we found that loss of a single copy of Fbxo9 was sufficient to cause increased aggressiveness in AML tumor cells." (PMID 31684170, 2019). "Consequently, cKO mice had a greater expression of cKit in BM upon sacrifice, indicating a greater tumor burden in the BM upon the loss of one or both Fbxo9 alleles." (PMID 31684170, 2019). "Mechanistically, FBXO9 directly binds to PD-L1 protein and enhances its degradation via ubiquitination, thereby impeding PD-L1 maturation and tumor immune evasion." (PMID 41646985, 2026). "We found that increased expression of FBXO9 suppresses tumor growth and promotes cytotoxic T cell activation in vivo." (PMID 41646985, 2026). "Immunohistochemistry analysis confirmed reduced FBXO9 expression in tumor tissues compared with that in adjacent normal tissues (P < 0.0001), which was consistent with our mRNA expression data." (PMID 38486234, 2024). "The results show that KRT8, PSMD2, TRIM28, and UBE2V2 are significantly overexpressed in tumor tissues, while the expression level of FBXO9, MYLIP, and RNF180 is significantly reduced in LUAD (p < 0.05)." (PMID 35711913, 2022). "Our results showed that both FBXO9 knockdown and lenvatinib treatment inhibited tumorigenicity, and knockdown of FBXO9 enhanced the tumor growth inhibition of lenvatinib." (PMID 35847937, 2022). "To further elucidate the effect of loss of Fbxo9 in AML, we treated cultured tumor cells with varying concentrations of the proteasome inhibitor bortezomib." (PMID 31684170, 2019). "While many other F-box proteins have been shown to have solely oncogenic or tumor suppressor roles, FBXO9 is among a few select members of the family that can function in both capacities." (PMID 31684170, 2019). "The evolutionarily conserved protein FBXO9 acts as a substrate receptor for the SKP1-cullin-1-RBX1 ubiquitin ligase and is implicated in cancer, exhibiting either tumor-suppressive or oncogenic effects depending on the specific tumor type." (PMID 38486234, 2024). "This insight enhances our understanding of the potential pathological implications of abnormally low FBXO9 expression in tumor tissues because it may lead to uncontrolled activation of Wnt signaling." (PMID 38486234, 2024). "Interestingly, these data demonstrated that CRISPR KO of FBXO9 led to a CERES project score of ~−0.2; this trend is similar to BRCA1 and BRCA2, which are well-known tumor suppressors associated with DNA damage repair." (PMID 38136595, 2023). "Lastly, evidence supporting our speculation regarding the potential role of FBXO9 as a tumor suppressor is still limited." (PMID 38136595, 2023). "Furthermore, FBXO9 exerts a tumor-promoting effect in HCC by downregulating FBXW7, thereby increasing the protein levels of FBXW7 oncogenic substrates, such as mTOR." (PMID 35847937, 2022). "As FBXO9 is an E3 ligase highly expressed in HSCs (the tumor-initiating population), we first explored the possibility that loss of its expression would result in changes to HSPC function that might lead to development of AML." (PMID 31684170, 2019). "To determine whether Fbxo9 is acting only in a tumor-initiating fashion or if it also has a role in tumor maintenance, we carried out a secondary transplantation." (PMID 31684170, 2019). "Moreover, our results implied that FBXO9 might be a potential cancer suppressor for OV as it is significantly downregulated in primary OV lesions, and such tumor suppression is likely through interplay with DNA damage repair genes." (PMID 38136595, 2023).